TLR4 (toll like receptor 4)
Diseases named in the same sentence as TLR4 in open-access papers (continued):
Sharing a sentence is not in itself a finding about the gene and the disease.
breast cancer (continued). "A loss of TLR4 or a mutated allele, such as those found in some breast cancer patients, diminishes the interaction between OXP and HMGB1; relapse after chemotherapy in these patients is more common than in those with a normal TLR4 allele." (PMID 36499737, 2022). "For instance, HMGB1 can induce ICD through interaction with TLR4, which determines the chemo- or radio-resistance of breast cancer." (PMID 35637945, 2022). "Next, we also investigated the expression of TLR4 in normal and different intrinsic subtypes of breast cancer by using the same cohort of patients and normal samples." (PMID 33969603, 2022). "The HMGB1/TLR4 axis ultimately modifies the intrinsic tumor properties and host immune response in the tumor microenvironment, leading to breast cancer metastasis." (PMID 35637945, 2022). "TLR4 activation by an alternative ligand paclitaxel significantly increased lymphatics and subsequent node metastasis in breast cancer models, in line with the reports demonstrating TLR4 prominent role in M-LECP differentiation and induction of Th2 cytokines." (PMID 35442077, 2022). "(b) LPS increases S100A7 expression in breast cancer cells that regulate TLR4 and RAGE expression and modulate breast tumorigenesis." (PMID 33969603, 2022). "To analyze the patient prognosis according to the expression of S100A7 and TLR4 based on tumor‐intrinsic features, we mined the KM plotter [breast cancer] database." (PMID 33969603, 2022). "Overall, increased level of LPS in the mammary tumor was found to be positively associated with S100A7 and inversely correlated with TLR4 expression." (PMID 33969603, 2022). "Considering the crosstalk between innate and adaptive immunity, we addressed the functional role of TLR4 in the immunocompetent 4T1 mammary tumor model." (PMID 35469015, 2022). "Different microbial products and TLR4 agonists have demonstrated the crucial role of TLR4 signaling in regulating tumor growth, survival, and progression in colonic, pancreatic, liver, and breast cancers." (PMID 35884586, 2022). "The purported ortholog receptor of resistin, TLR4, is usually expressed and has recently been identified on multiple tumor cells, including gastric cancer, breast cancer and lung adenocarcinoma." (PMID 36497484, 2022). "Previously, we reported that stimulation with the TLR4 agonist LPS reduced microglia (MG)-induced invasion of MCF-7 human breast-cancer cells in a modified Boyden chamber assay." (PMID 36224342, 2022). "Stemness of luminal breast cancer cells was enhanced depending on TLR4 stimulated by high-mobility group box 1 (HMGB1) from autophagic CAFs indicating high LC3II/TLR4 to be poor prognosis markers for breast cancer." (PMID 33990205, 2021). "P. aeruginosa is a potent producer of LPS, and its stimulation by TLR4 has also been revealed to promote breast cancer metastases through Akt activation." (PMID 34604233, 2021). "Chinese propolis, as well as CAPE, inhibits breast cancer cell proliferation in the inflammatory microenvironment by inhibiting the Toll-like receptor 4 (TLR4) signal pathway." (PMID 34444754, 2021). "In our previous research, we found that bacterial lipopolysaccharide (LPS) promoted the metastasis of breast cancer cells in vitro and in vivo by activating the TLR4/MyD88/NF-κB signaling pathway." (PMID 34475958, 2021). "Previous studies have suggested that DMDD shows significant antitumor potential against human breast cancer by inhibiting the TLR4/MyD88/NF-κB and MAPK pathway in vitro and in vivo." (PMID 33613291, 2021). "Astragalus polysaccharides, a kind of traditional Chinese medicine, can modulate macrophages through TLR4/MyD88 signaling to enhance the immune response in breast cancer patients." (PMID 34141706, 2021).
breast cancer (continued). "The engagement of TLR4 expressed by human breast cancer cells results in increased production immunosuppressive factors such as NO, VEGF, and MMPs, thereby promoting the tumor invasion." (PMID 33747948, 2021). "Although TLR4 plays an essential part in breast cancer progression, the role of its accessory protein, MD2, known for several years as an essential co-factor for TLR4 signaling, has not yet been clarified." (PMID 33733435, 2021). "TLR4/MyD88 pathway has been found to be upregulated in breast cancer cell line with high invasion rate as compared to the breast cancer cell line with lower invasion rate." (PMID 34671606, 2021). "Among them is the TLR4/myD88 pathway, which is expressed in tumor cells and has been linked to axillary lymph node metastasis and histological grade, while the inhibition of TLR4 expression impedes proliferation and promotes apoptosis of breast cancer cells." (PMID 34299224, 2021). "For example, paclitaxel, a widely used anticancer drug, has been found to promote breast cancer metastasis in a Toll‐like receptor 4 (TLR4) dependent manner." (PMID 33369155, 2021). "This study showed that FAM49B can activate the proliferation and metastasis of BC cells through the ELAVL1/Rab10/TLR4 pathway, and the malignant degree and aggressiveness of breast cancer with high expression of FAM49B were significantly increased." (PMID 34645466, 2021). "A study showed that TLR4 promotes tumor metastasis and is closely related to poor prognosis in breast cancer." (PMID 32095158, 2020). "In line with previous results, our results revealed that the migration and invasion of AMPKαlKO A459 lung cancer, AMPKα1KO MDA-MB-231 breast cancer, and AMPKα1KO MCF-7 breast cancer cells were significantly attenuated by TLR4 stimulation." (PMID 33172060, 2020). "The activation of TLR4 promotes integrin alpha V beta 3-mediated adhesion and migration of breast cancer cells." (PMID 33002094, 2020). "In this context, AMPKα1-knockout lung or breast cancer cells exhibited the attenuation of cancer cell migration and invasion induced by TLR4 simulation." (PMID 33172060, 2020). "The results above demonstrated that AT-I suppressed tumorigenesis in breast cancer cells via inhibiting TLR4-mediated NF-κB signaling pathway." (PMID 33363472, 2020). "To study the important role of TLR4/NF-κB pathway in breast cancer, we assessed the expression of TLR4 and NF-κB among normal breast tissues and different TNM-stages breast cancer tissues using tissue microarray and immunohistochemistry technology." (PMID 33363472, 2020). "In the present study, we found that the expression of TLR4, MyD88, p-NF-κB p65, p-IκBα and p-IKKα/β in breast cancer cells was significantly down-regulated after AT-I treatment." (PMID 33363472, 2020). "TLR4 and NF-κB levels in breast cancer cells were significantly higher than that in mammary epithelial cells." (PMID 33363472, 2020). "In breast cancer cells and primary breast cancer tissues from patients, TLR4 expression was found to be up-regulated both at mRNA and protein levels, and significantly correlated with the high incidence of lymph node metastasis." (PMID 33363472, 2020). "The results showed that TLR4 and NF-κB were over expressed in breast cancer, and correlated with the TNM-stages." (PMID 33363472, 2020). "TLR4 signaling in colorectal cancer and breast cancer cells promotes invasion and metastasis of these cells." (PMID 32733461, 2020). "TLR4 and NF-κB were up-regulated in human breast cancer tissues and correlated with advanced TNM-stages." (PMID 33363472, 2020). "The results showed that TLR4 and NF-κB levels in breast cancer tissues were significantly higher than that in normal breast tissues." (PMID 33363472, 2020).
breast cancer (continued). "Paclitaxel-induced TLR4 signaling in murine and human breast cancer cells results in the production of the proinflammatory cytokines IL-1ß and IL-6, which promotes the expansion of MDSCs in the bone marrow and spleen as well as their recruitment to the TME." (PMID 32733461, 2020). "We found that TLR4 and NF-κB were over expressed in human breast cancer tissues, and activation of TLR4/NF-κB pathway was correlated with advanced TNM-stages." (PMID 33363472, 2020). "We now show that this rapid uptake is significantly attenuated by CLI‐095, the specific inhibitor of TLR4 in two breast carcinoma cell lines both of which express TLR4." (PMID 33073533, 2020). "A recent study showed that lipopolysaccharide (LPS) signaling activates AKT via TLR4 to promote breast cancer metastasis." (PMID 31844158, 2019). "Our data showed that TLR4 is expressed in LECs, and its expression was increased after co-culturing with LC breast cancer cells." (PMID 31390756, 2019). "The acquired TLR4-mediated paclitaxel resistance in advanced breast cancer is explained partly by the paracrine effect of IL-8 release." (PMID 30175384, 2018). "IL-8 showed increased expressions in paclitaxel-treated advanced breast cancer and this over-production effect was inhibited in TLR4-silenced cells." (PMID 30175384, 2018). "Brown reviewed that NF-κB pathway activation upregulates TGM2 level in the breast cancer, and Kiziltas reported that NF-κB pathway activation is the common downstream pathway of TLR4 signal pathway activation in the liver." (PMID 29321784, 2017). "Further studies for LPS/TLR4-TOPK signaling cascades are required for elucidation of molecular mechanism leading to breast cancer metastasis." (PMID 28212583, 2017). "TLR4 and MyD88 have been demonstrated over expression in breast cancer, suggesting the possible role of TLR4 signaling pathway in tumor microenvironment." (PMID 29029545, 2017). "The role of TLR4, specific receptor for LPS, in tumor progression has been studied in various cancers involving colon, pancreas, liver and breast cancers." (PMID 28212583, 2017). "Consistently, knockdown of TLR4 via TLR4 siRNA in human breast cancer cell line MDA-MB-231 induced a decreased secretion of cytokines including IL-6 and IL-8, and a inhibition in proliferation and survival of these cells." (PMID 29029545, 2017). "It is reported that TLR4 is over-expressed in the majority of clinical breast cancer and involvement in breast cancer development and progression." (PMID 28950845, 2017). "It has been reported that activation of TLR4 on metastatic breast cancer cells stimulates invasiveness, whereas silencing of TLR4 enhances tumor progression and metastasis in a murine model of breast cancer." (PMID 28212583, 2017). "Here we reveal that TOPK functions as an effector in breast cancer cell invasion induced by LPS/TLR4 signaling." (PMID 28212583, 2017). "This evidence from orthotopic breast cancer models demonstrates that TLR4 activation of BM myeloid cells generates functional M-LECP capable of expanding tumor lymphatic vasculature in vivo." (PMID 28598999, 2017). "Clinicopathological parameters further revealed that TLR4 overexpression in human breast cancer tissues was correlated to lymph node metastasis." (PMID 26863029, 2016). "It is documented that TLR4 activation promotes carcinogenesis and resistance to chemical treatments in breast cancer, whereas blocking TLR4 activation can slow breast cancer growth and prolong survival." (PMID 26771524, 2016). "The finding that LPS potently induced apoptosis in M13MDA435-1 and -3 hybrid cells via an IFN-β dependent mechanism still remains ambiguous, which also applies for the role of LPS and TLR4 signaling in breast cancer." (PMID 27187369, 2016). "TLR4-mediated cancer growth involved in breast tumor progression and downregulation of TLR4 prevented breast cancer progression and survival." (PMID 26675260, 2016).
breast cancer (continued). "In the setting of cancer, HMGB1 signalling through its innate immune system receptors TLR2 and TLR4 (toll-like receptors 2 and 4) is important for an antitumour immune response in breast cancer patients." (PMID 26948869, 2016). "This means that three out of the four TN breast cancer cell lines had the necessary proteins for a functional TLR4 signal to occur." (PMID 26392082, 2015). "In support of this, previous studies have shown that TLR4 expression promotes metastasis in a breast cancer model, an effect that was even enhanced by Paclitaxel." (PMID 26392082, 2015). "Our previous study demonstrated that PSP has an immunoregulatory effect through the TLR4 signaling pathway in PBMCs from breast cancer patients." (PMID 26032186, 2015). "Recent studies have demonstrated that TLR4 is expressed in a wide variety of tumors, including breast cancers, and that LPS-TLR4 signaling promotes cancer progression." (PMID 25691060, 2015). "Studies regarding TLR4-antagonist therapies should be focusing on ER/PR-negative breast cancer particularly." (PMID 26392082, 2015). "The cytoplasmic localization of TLR4 in breast cancer cells was supported by transfection of breast cancer cells using a green fluorescent protein (GFP)-tagged TLR4 plasmid (pUNOI-hTLR4-GFP)." (PMID 26392082, 2015). "Using a carefully validated TLR4-specific antibody for immunohistochemistry (IHC), we found that TLR4 protein expression was primarily present in breast cancers of ER/PR-negative phenotype." (PMID 26392082, 2015). "Using three cell lines of ER+ phenotype and four cell lines of the TN phenotype, we further showed that the expressed TLR4 was biologically active and hence responding to both PAMPs and DAMPs, primarily in the TN breast cancer cell lines." (PMID 26392082, 2015). "Stimulation of TLR2/4 in vitro induced expression of pro-inflammatory genes and a gene expression analysis of primary breast cancers showed a strong correlation between TLR4 expression and expression of pro-inflammatory mediators." (PMID 26392082, 2015). "By contrast, recent studies using a potential TLR4 agonist demonstrated enhanced survival of mice in a model of tumor resection, suggesting that the contributions of TLR4 to breast cancer progression are complex." (PMID 26106384, 2015). "Accordingly, the function of the TLR4-MyD88 pathway in tumor biology provides a new potential target for breast cancer therapy." (PMID 25360699, 2014). "The capacity to limit the growth and development of metastatic tumor in a stringent 4T1 breast cancer model makes this novel TLR-4 agonist particularly attractive." (PMID 25432242, 2014). "This study evaluated the prognosis of breast cancer patients based on contributors to the innate immune response: myeloid differentiation primary response 88 (MyD88) and Toll-like receptor 4 (TLR4)." (PMID 25360699, 2014). "With an invasion assay, our findings indicated that TLR4 played an effective role in the invasive potential of MDA-MB-231 human breast cancer cells." (PMID 25299052, 2014). "High levels of TLR4 staining were observed in 94 of the 205 breast cancer patients, and low levels of staining were observed in the other 111 cases." (PMID 25360699, 2014). "TLRs are the main innate immune pattern recognition receptors, and many researchers have closely investigated the molecular mechanism of TLR4, which promotes tumorigenesis, invasion, metastasis, recurrence, and drug resistance in breast cancer." (PMID 25360699, 2014). "Recent studies showed that TLR4 was expressed not only on immune cells but also on cancer cells such as cervical cancer, lung cancer, and breast cancer." (PMID 25179302, 2014). "TLR4 induction, signaling, and activation in numerous cancers such as breast cancer, colon cancer, ovarian, and prostate cancer were also identified." (PMID 25177689, 2014).
breast cancer (continued). "Real time PCR revealed that the expression of TLR4 on both human breast cancer cell lines was blocked by TLR4 antagonist which was added prior to the addition of LPS in ER+LPS group compared with LPS group (P<0.05)." (PMID 25299052, 2014). "Combined with clinicopathological parameters, TLR4 was overexpressed in human breast cancer tissue and correlated with lymph node metastasis." (PMID 25299052, 2014). "We also explored TLR4 expression in breast cancer tissue and the relation between TLR4 expression and tumor metastasis." (PMID 25299052, 2014). "Studies from our laboratory on carcinogenic polyaromatic hydrocarbon 7,12-dimethylbenz(a)anthracene (DMBA) have demonstrated that cell mediated immunity to DMBA was dependent on TLR4 and had a protective effect against mammary tumor development." (PMID 24904578, 2014). "Our data reported herein identify the immunostimulatory agent, Immunomax® as a TLR-4 agonist with anti-tumor activity in the stringent 4T1 murine breast cancer model, which recapitulates human micro-metastatic disease." (PMID 25432242, 2014). "Tumor specimens confirmed that TLR4 was highly expressed in human breast cancer tissues as similar as others while normal breast tissue hardly expressed TLR4." (PMID 25299052, 2014). "Consistent with our results, TLR4 activation has been reported to accelerate breast cancer growth and reduce survival." (PMID 25360699, 2014). "This study investigated the expression and biological role of TLR4 in human breast cancer metastasis." (PMID 25299052, 2014). "A significant positive correlation was observed between MyD88 and TLR4 immunostaining in the tissue samples of the patients (p<0.001), which is consistent with the results obtained using breast cancer cells lines." (PMID 25360699, 2014). "We then investigated the relationship between the expression levels of MyD88 and TLR4 in clinical breast cancer samples by immunohistochemical staining." (PMID 25360699, 2014). "Accumulated evidence suggests that TLR4 is expressed not only by immune cells but also by a variety of cancer cells such as cervical cancer, breast cancer, and lung cancer." (PMID 25179302, 2014). "For instance, TLR4 activation on metastatic breast cancer cells promoted the αvβ3-mediated adhesion and invasiveness of cancer cells." (PMID 25299052, 2014). "In the present study, we analyzed the expression of MyD88 and TLR4 in 205 cases of breast cancer and evaluated their correlation with the clinicopathological characteristics and prognoses of these patients." (PMID 25360699, 2014). "Both of the breast cancer cell lines expressed TLR4 mRNA detected by RT-PCR and protein was detected by western blotting, and after LPS stimulation, the increased expression of TLR4 was clearly observed." (PMID 25299052, 2014). "Studies have shown that lipopolysaccharide (LPS) ligation to TLR4 promotes tumor cell adhesion and invasion in a murine model by acting NF-kappa B, and the silencing of TLR4 increases tumor progression and metastasis in a murine model of breast cancer." (PMID 24376595, 2013). "For example, prior studies have identified polymorphisms in TLR4 (rs4986790) and TNF (rs361525 and rs1800629) that affect breast cancer risk." (PMID 23634849, 2013). "Knockdown of TLR4 gene in MDA-MB-231 resulted in a dramatic reduction of breast cancer cell viability and inhibition of IL-6 and IL-8 cytokines compared with vector control." (PMID 22295250, 2012). "Further, it has been demonstrated that the TLR4 Asp299 polymorphism affects the binding of HMGB1 to TLR4 and predicts early relapse after chemotherapy in breast cancer patients." (PMID 21854645, 2011). "To date, we are the first to show the role of MTDH in the TLR4 signaling pathway in breast cancer cell line, MDA-MB-231 cells." (PMID 22195048, 2011). "In that study, on French breast cancer patients, the 299G form of TLR4 showed reduced binding to HMGB1 and a correlation with faster relapse after radiotherapy." (PMID 21931695, 2011).